PTGES3L-AARSD1 (PTGES3L-AARSD1 readthrough)
Description:
Functions in trans to edit the amino acid moiety from incorrectly charged tRNA(Ala).
Tractability: PROTAC: ubiquitination databases record sites on it; its protein half-life has been measured.
Gene: Protein-coding gene on chromosome 17 (42,950,526 to 42,980,528, reverse strand). Ensembl gene ENSG00000108825.
Subcellular location: Cytoplasm
Subcellular location (Human Protein Atlas): Cytosol; Nuclear membrane
Gene Ontology:
Molecular function: Ser-tRNA(Ala) deacylase activity; alanine-tRNA ligase activity; aminoacyl-tRNA deacylase activity; aminoacyl-tRNA ligase activity; ATP binding; nucleic acid binding; nucleotide binding
Biological process: regulation of translational fidelity; alanyl-tRNA aminoacylation; aminoacyl-tRNA metabolism involved in translational fidelity; tRNA aminoacylation
Cellular component: nucleus; cytoplasm
Genetic constraint (gnomAD): Loss-of-function variants: 55 observed, 74.5 expected, observed/expected ratio (o/e) 0.74, 90% interval 0.59 to 0.92. The upper end of that interval is the gene's LOEUF score, 0.92, which puts it in group 3 of 6, group 1 being the genes least tolerant of losing a copy. Missense variants: 672 observed, 728.39 expected, observed/expected ratio (o/e) 0.92, 90% interval 0.87 to 0.98. Synonymous variants: 235 observed, 266.67 expected, observed/expected ratio (o/e) 0.88, 90% interval 0.79 to 0.98.